PTX3 (pentraxin 3)
Diseases named in the same sentence as PTX3 in open-access papers (continued):
Sharing a sentence is not in itself a finding about the gene and the disease.
gastric cancer (continued). "Moreover, PTX3 induced bone metastatic gastric cancer cell proliferation through activation of Akt and inhibited apoptosis while PTX3 silencing reduced proliferation and increased apoptosis in HTB135 cells." (PMID 27458153, 2016). "In HTB135 cells, PTX3 silencing completely obviated the BDNF-induced increase in HTB135 cell–OB interactions (P <0.05), suggesting that BDNF-induced PTX3 is the predominant factor responsible for the interaction of bone metastatic gastric cancer cells with OBs." (PMID 27458153, 2016). "Similarly, contrasting roles for PTX3 have been observed in gastric cancer under TNF-α stimulation." (PMID 41479916, 2025). "We hypothesize that PTX3 might serve as a new target for gastric cancer treatment." (PMID 32194791, 2020). "Therefore, PTX3 levels might possibly act as a precise anti-oncogene incorporated in gastric carcinoma advancement." (PMID 32194791, 2020). "Additionally, overexpression of PTX3 might decrease the gastric carcinoma migration as well as invasion capacity mediated by TNF-α according to our data." (PMID 32194791, 2020). "In conclusion, we have demonstrated a functional interaction between BDNF/TrkB and PTX3 in advanced gastric cancer and have provided evidence that these proteins may enhance the interaction between bone metastatic gastric cancer cells and OBs, thereby leading to osteolysis." (PMID 27458153, 2016). "Therefore, we reasoned that BDNF-derived PTX3 induction in bone metastatic gastric cancer cells may upregulate RANKL expression in OBs, thereby stimulating OC formation." (PMID 27458153, 2016). "PTX3, elevated by BDNF/TrkB axis, is related to bone metastatic status of gastric cancer by enhancing gastric cancer-osteoblastic niche interactions." (PMID 41479916, 2025). "Another study reinforced PTX3’s role in promoting migration of gastric cancer cells and identified its ability to recruit macrophages through TNF-α/NF-κB activation-driven PTX3 upregulation." (PMID 41479916, 2025). "Since PTX3 can be regulated by TNF-α, we believed that PTX3 contributes in gastric carcinoma advancement facilitated by exogenous TNF-α." (PMID 32194791, 2020). "PTX3 protein, which is induced by the BDNF/TrkB axis, facilitates the interaction of gastric cancer cells with OBs, thereby suggesting a potential role of PTX3 in establishing bone metastatic footholds of gastric cancer cells in BM." (PMID 27458153, 2016). "One study emphasized PTX3’s inhibitory role in migration and invasion in gastric cancer cells (BGC-823 and SGC-7901), while another study highlighted its role in promoting migration of the HTB135 cell line, a bone-metastatic human gastric cancer cell line." (PMID 41479916, 2025). "PTX-3 overexpression, infiltration of CD11b+ macrophages, TNF-α, and NF-ƙB activation were noted in human advanced gastric cancer tissues and contributed to gastric cancer-related inflammation." (PMID 36499628, 2022). "In order to inspect the link between PTX3 and TNF-α in gastric cancer, we established that exogenous TNF-α might directly influence the manifestation of the PTX3 in the BGC-823 as well as SGC-7901 cells." (PMID 32194791, 2020). "Currently, no reports regarding the expression of PTX3 in gastric cancer and its paracancerous tissues have been published." (PMID 32194791, 2020). "We infer the correlation between PTX3 and TNF-α during the progress of gastric cancer cells, which provides a foundation of TNF-α could regulate PTX3 in a negative way in vitro as well as in vivo." (PMID 32194791, 2020). "Furthermore, PTX3 controlled the capability of cell migration, invasion as well as epithelial-mesenchymal transition (EMT) in gastric cancer cell lines mediated by TNF-α." (PMID 32194791, 2020). "The present study indicates that primary gastric cancers express lower levels of PTX3 than nonmalignant tissues; however, bone metastatic gastric cancer cells were found to express elevated levels of PTX3." (PMID 27458153, 2016).
gastric cancer (continued). "Given the upregulation of BDNF/TrkB and PTX3 expression observed in bone metastatic gastric cancers, we assumed that BDNF, a specific ligand of TrkB, induces PTX3 expression via TrkB signaling in bone metastatic gastric cancer cells." (PMID 27458153, 2016). "Different mechanisms appear in gastric cancer, as PTX-3 promotes macrophage recruitment, cell invasiveness, and metastatic properties, while in esophageal squamous cell carcinomas and colorectal cancer, hypermethylation leads to PTX-3 gene silencing concomitantly with tumor growth." (PMID 36499628, 2022). "In addition, although the mechanism of action of TNF-α in tumors has been widely proven during recent years, studies have not mentioned the interaction between TNF-α and PTX3 in gastric cancer metastasis and EMT." (PMID 32194791, 2020). "Nevertheless, there was no proof to recognize the link of the PTX3 with TNF-α in gastric cancer." (PMID 32194791, 2020). "Collectively, these findings indicate that compared with nonmalignant specimens, PTX3 expression is repressed in patients with gastric cancer, although elevated PTX3 expression in gastric cancer may correlate with relapse-correlated metastasis." (PMID 27458153, 2016). "Taken together, these results indicate that in addition to its positive effect on the interaction between bone metastatic gastric cancer cells and OBs, BDNF may play a functional role in enhancing osteoclastogenesis by upregulating PTX3, which in turn promotes RANKL production from OBs." (PMID 27458153, 2016). "Conversely, PTX3 at a concentration of 100 ng/ml markedly stimulated the transcriptional expression of TrkB mRNA but not BDNF mRNA in HTB135 cells, implying the presence of reciprocal regulation between PTX3 and TrkB expression in bone metastasis of gastric cancer." (PMID 27458153, 2016).
systemic lupus erythematosus (18 papers, 2011 to 2025). An autoimmune multi-organ disease typically associated with vasculopathy and autoantibody production. "High circulating PTX3 levels were associated with vascular injury in systemic lupus erythematosus patients, thus increasing the dysfunction on the vascular endothelium." (PMID 31057548, 2019). "Together, PTX3 specifically suppresses autoimmune lung disease that is associated with systemic lupus erythematosus." (PMID 21637713, 2011). "To evaluate a potential immunoregulatory role of PTX3 in autoimmunity we crossed Ptx3-deficient mice with Fas-deficient (lpr) C57BL/6 (B6) mice with mild lupus-like autoimmunity." (PMID 21637713, 2011). "Our group demonstrated that anti-PTX3 antibodies reduced the burden of PTX3 deposition in the kidney and counteracted nephritogenic antibodies in lupus-prone mice." (PMID 39340807, 2025). "Serum PTX3 levels were shown to correlate with progression of autoimmune diseases (childhood-onset systemic lupus erythematosus (Quismorio Jr." (PMID 35989325, 2022). "Furthermore, PTX3 immunization of lupus-prone mice resulted in anti-PTX3 antibody occurrence and was associated with delayed and milder lupus-like nephritis and increased overall and disease-free survival, thus providing evidence for an immunomodulatory capacity of anti-PTX3 antibodies." (PMID 30740098, 2019). "Such as in systemic sclerosis and systemic lupus erythematosus, serum PTX3 level of patients was significantly increased." (PMID 29675428, 2018). "Recent study with the murine models of lupus also demonstrated that immunization with PTX3 and subsequent development of anti-PTX3 auto-antibodies significantly delayed occurrence of nephritogenic antibodies, decreased proteinuria, and increased survival." (PMID 28393653, 2017). "Other studies have shown that PTX3 levels are higher in several IRDs (RA, PsA, AS, polymyalgia rheumatica, giant cell arteritis, systemic lupus erythematosus and small vessel vasculitis) compared to control groups." (PMID 28225768, 2017). "There were significant correlations between serum PTX3 levels and Systemic Lupus Erythematosus Disease Activity Index (SLEDAI) scores, serum creatinine value, renal pathological activity indices, and serum complement 3 (C3) in active lupus nephritis patients." (PMID 26817892, 2016). "In patients who experienced a clinical relapse, an increase in PTX3 levels followed the lupus flare." (PMID 26613049, 2015). "This view is supported by data from an in vivo murine model of systemic lupus erythematosus, where it has been shown that PTX3 fosters the rapid clearance of apoptotic T cells by peritoneal macrophages." (PMID 23316195, 2012). "Both of these mechanisms are known to be involved in autoimmunity and autoimmune tissue injury, e.g. in systemic lupus erythematosus, but a contribution of PTX3 is hypothetical." (PMID 21637713, 2011). "Indeed, lupus prone NZB/NZW mice immunized with PTX3 produce anti-PTX3 Abs and have a delayed occurrence of nephritogenic Abs, a decreased proteinuria, and an increased survival." (PMID 33664737, 2020). "An integrate viewpoint suggested that PTX3 responsiveness lupus is possible and it could be speculated that PTX3 may play a role as a biomarker of disease activity." (PMID 26613049, 2015). "Furthermore, PTX3 is redundant for the production of lupus autoantibodies in these mice, albeit it fosters the clearance of apoptotic cells and (thereby) inhibits the expansion of CD4/CD8 double negative T cells." (PMID 21637713, 2011). "The presence of preformed PTX3 in neutrophil granules, similar to MPO and PR3, and the detection of circulating anti-PTX3 aAbs in other autoimmune disease such as systemic lupus erythematosus, lead us to investigate whether anti-PTX3 aAbs could be detected in the sera of AAV patients." (PMID 26797217, 2016).
systemic lupus erythematosus (continued). "High levels of PTX3 have been found in active AAV, large vessel vasculitis, and connective tissue diseases (CTDs), as in systemic lupus erythematosus (SLE)." (PMID 39257888, 2024). "In order to test whether Ptx3 serves as a modifier gene on established SLE we generated Ptx3-deficient C57BL/6lpr/lpr (B6lpr) mice and compared the phenotype with wild type B6lpr mice, an autoimmune mouse strain that develop lupus autoantibodies but only mild SLE manifestations in kidneys and lung." (PMID 21637713, 2011). "PTX3 levels were high in patients with small vessel vasculitis and rheumatoid arthritis, but not in those with systemic lupus erythematosus." (PMID 31057548, 2019). "Since there was a positive correlation between the PTX3 plasma concentration and the disease activity indexes, we suspected that patients with major organ damage such as APS lupus or lupus nephritis could have higher PTX3 levels." (PMID 26613049, 2015). "In addition lack of PTX3 on lupus prone genetic background (B6lpr) accelerates the evolution of autoimmune lung disease, which is associated to selective expansion of CD4/CD8 double negative “autoreactive” T cells." (PMID 23316195, 2012). "However, abnormalities of B cell differentiation against PTX3 have not been characterized in systemic lupus erythematosus (SLE)." (PMID 30740098, 2019). "Lack of PTX3 impaired the phagocytic uptake of apoptotic T cells into peritoneal macrophages and selectively expanded CD4/CD8 double negative T cells while other immune cell subsets and lupus autoantibody production remained unaffected." (PMID 21637713, 2011).
autoimmune disease (17 papers, 2011 to 2025). A disorder resulting from loss of function or tissue destruction of an organ or multiple organs, arising from humoral or cellular immune responses of the individual to their own tissue constituents. "Antibodies directed against CRP, SAP, and PTX3 have been detected in various autoimmune diseases, especially in SLE and ANCA-associated vasculitis (AAV)." (PMID 33664737, 2020). "In a mechanistic point of view, studies are required to determine the potential pathogenic role of anti-PTX3 and whether they should be targeted if they are more than just bystanders in severe autoimmune diseases." (PMID 33664737, 2020). "Antibodies directed against PTX3 have been detected in various autoimmune diseases, especially in SLE and AAV." (PMID 39108259, 2024). "PTX3 (pentraxin 3) serves as a biomarker for several autoimmune diseases, participating in inflammation regulation and fibrocyte differentiation." (PMID 34290731, 2021). "In a meta-analysis, PTX3 levels were found to be high in the case of autoimmune diseases when compared with normal controls." (PMID 33529185, 2021). "Anti-PTX3 Abs have been detected in other autoimmune diseases such as SSc, SS and RA, but at a frequency similar to healthy subjects." (PMID 33664737, 2020). "From a diagnostic point of view, PTX3 elevation in the circulating blood marks the occurrence of inflammatory events in blood vessels and might find a specific niche in clinical practice as a tool to identify vasculitic subsets among patients with autoimmune diseases." (PMID 31191526, 2019). "PTX3 levels were significantly higher in patients with systemic inflammatory immune-mediated and autoimmune diseases (2.33 ng/ml, IQR: 1.26–4.89, n = 287) than in HCs (1.22 ng/ml, IQR:0.80–1.98, n = 79; p < 0.001)." (PMID 31191526, 2019). "Pentraxin 3 (PTX3), is an acute-phase reactant produced by innate immune cells in response to inflammatory stimuli, recently emerged as an interesting novel serological biomarker for various autoimmune diseases." (PMID 36911748, 2023). "Since TAK is a rare autoimmune disease, contradictory results on PTX3 true value on disease activity assessment may be due to the small sample size." (PMID 33529185, 2021). "A number of studies have confirmed that serum levels of PTX3 were elevated in inflammatory and autoimmune diseases, suggesting that PTX3 may be a potential serological marker." (PMID 29675428, 2018). "However, increased PTX3 levels can exacerbate persistent and autoimmune diseases, such as chronic heart and lung diseases." (PMID 28619036, 2017). "Vice versa, loss-of-function mutations in the Ptx3 gene might represent a genetic risk factor for pulmonary (but not renal) manifestations of systemic lupus or other autoimmune diseases." (PMID 21637713, 2011). "In autoimmune diseases such as SLE, PTX3 may promote the clearance of immune complexes or regulate immune responses by activating or modulating the complement pathway." (PMID 40131879, 2025). "A recent systematic review also confirmed that both serum and plasma levels of PTX3 in autoimmune diseases were significantly higher than in normal controls." (PMID 28225768, 2017).
hepatocellular carcinoma (17 papers, 2019 to 2025). A malignant tumor that arises from hepatocytes. "Carmo and colleagues found in a multivariate analysis that the PTX3 (rs2305619) A/A genotype was associated with hepatocellular cancer in patients infected with hepatitis C virus and that those individuals were twice predisposed to have carcinoma." (PMID 36499628, 2022). "PTX3 rs2305619 polymorphism has been reported to be associated with Child-Pugh scores B and C in hepatocellular carcinoma individuals." (PMID 33967610, 2021). "Indeed, PTX3 facilitated progression of different cancers, and PTX3 expression in hepatocellular carcinoma (HCC) tissues was positively associated with shorter survival time of the patients." (PMID 32078718, 2020). "PTX3 overexpression accelerates tumor metastasis and suggests poor prognosis in hepatocellular carcinoma by driving epithelial-mesenchymal transition." (PMID 39910672, 2025). "Moreover, elevated plasma levels of PTX3 have been linked to an increased risk of hepatocellular carcinoma (HCC) development in individuals with chronic HCV infection." (PMID 41462970, 2025). "Elevated levels of circulating PTX3 have been observed in several malignancies, including colorectal, lung, and hepatocellular cancers." (PMID 38542446, 2024). "In hepatocellular carcinoma, several tissue studies have shown that increased PTX3 boosted cell proliferation, invasion, and migration capacity." (PMID 34202354, 2021). "In hepatocellular carcinoma, PTX3 expression was analyzed after liver resection in tumoral and adjacent normal tissue and a higher PTX3 expression was observed in the tumoral area." (PMID 31019517, 2019). "Patients with hepatocellular carcinoma (HCC) showed higher PTX3 levels than individuals with fibrosis." (PMID 31019517, 2019). "Intratumoral expression of PTX3 was increased in lung cancer, primary brain tumors, and hepatocellular carcinoma versus non-neoplastic tissue, and this was also associated with worse prognosis." (PMID 41373493, 2025). "In hepatocellular carcinoma (HCC), PTX3 has been implicated in tumor metastasis and poor prognosis." (PMID 41479916, 2025). "The complicated regulatory role of PTX-3 in hepatocellular cancer could be explained through TNF-α and IL-1β increased levels that further progress concomitant with the disease." (PMID 36499628, 2022). "In an in vitro study involving hepatocellular carcinoma (HCC) cell lines, PTX3 was shown to facilitate tumor cell proliferation, growth, and epithelial–mesenchymal transition (EMT)." (PMID 39594709, 2024). "Over-expression of PTX-3 increases macrophage chemotaxis, cellular proliferation, and EMT, therefore suggesting a pro-tumorigenic role in hepatocellular carcinoma." (PMID 36499628, 2022). "While several previous studies have evaluated serum PTX3 levels in the context of liver fibrosis and hepatocellular carcinoma (HCC), tissue-level expression has not been evaluated." (PMID 41462970, 2025). "PTX3 expression is rapidly induced by proinflammatory cytokines, such as TNF-α and IL-1β, and PTX3 has thus been suggested to be a biomarker in inflammation-related diseases such as chronic obstructive pulmonary disease (COPD), hepatocellular carcinoma and liver fibrosis." (PMID 38243273, 2024). "Likewise, serum PTX3 was not correlated with histological steatosis, inflammation, or fibrosis stage in patients with hepatocellular carcinoma (HCC)." (PMID 32078718, 2020).